MMP9 (matrix metallopeptidase 9)
Diseases named in the same sentence as MMP9 in open-access papers (continued):
Sharing a sentence is not in itself a finding about the gene and the disease.
tumor (continued). "In addition, the tumor also showed decreased matrix metalloproteinase 2 (MMP2) and matrix metalloproteinase 9 (MMP9) expression levels while there were increased E-cadherin levels." (PMID 32372949, 2020). "Using an in vitro BBB model, knockdown and overexpression experiments showed that HOXB9-dependent expression of MMP9 in NSCLC cells leads to reduced expression of junctional proteins in cultured human vascular endothelial cells and enhanced transmigration of tumor cells." (PMID 33411683, 2020). "The MMP-9 protein expression in CRC tissue is higher than in adenomas or the normal colon mucosa and its expression in a tumour tissue significantly correlates with clinical data: cancer grade, higher risk of disease recurrence and shorter survival of CRC patients." (PMID 32403316, 2020). "Several studies demonstrated that in different tumor tissues, TGF-beta could down-regulate the levels of MMP9." (PMID 33207819, 2020). "TDEs also cargo some pro-angiogenic factors such as vascular endothelial growth factor (VEGF), IL-8, matrix metalloproteinase 9 (MMP9) or hepatocyte growth factor, secreted by stromal cells, thereby inducing endothelial cell proliferation and facilitating tumor angiogenesis." (PMID 33291683, 2020). "In multivariate Cox regression analysis, MMP9 mRNA was an independent predictor of BCSS (p = 0.048; HR = 1.3; 95% CI 1.0–1.6) independent of the standard prognostic parameters of BC including tumour size, histological grade, nodal stage, and proliferative fraction as assessed by Ki67." (PMID 32445177, 2020). "Osthole (100, 150, and 200 μm) could downregulate the protein expression of MMP-9 and vimentin to suppress TGF-β dependent tumor invasion." (PMID 32028721, 2020). "Thus, curcumin and luteolin impair the migratory activity in tumor cells by the repression of the CXCL12/CXCR4 biological axis, as a consequence of the downregulation of MMP-9 by luteolin." (PMID 33195200, 2020). "This increased active MMP9 secretion was reduced by CD147 knockdown in the tumor cells, or by using the EVs of U-118 MG cells, which had no detectable CD147 levels." (PMID 32033611, 2020). "Secondly, MVs are able to enhance angiogenesis: They stimulate the expression of pro-angiogenic molecules [including matrix metalloproteinase (MMP)-9, VEGF, IL-8 and hepatocyte growth factor (HGF)] in tumor cells and drive capillary tube formation by stimulating endothelial cells." (PMID 31991775, 2020). "Tumors from CXCL8 overexpressing LNCaP cells exhibited increased tumor size, vasculature, and microvessel formation when compared to control cells, with CXCL8 overexpressing LNCaP cells also exhibiting enhanced invasiveness and MMP9 expression." (PMID 32585812, 2020). "FBN1, FN1, HGF, MMP9, THBS1, and VCAN may be new GC prognostic targets by affecting tumor purity, TMB, TME score, and multiple oncogenic signaling pathways." (PMID 33014013, 2020). "Upregulated CAF-derived versican can subsequently enhance cancer cell motility and invasion by activating the nuclear factor-κB (NF-κB) signaling pathway and inducing the expressions of CD44, MMP-9, and hyaluronan-mediated motility receptor (HMMR) in the surrounding tumor microenvironment." (PMID 30568223, 2019). "Moreover, sICAM-1 exposure also promoted tumor secretion of matrix remodeling factors uPA, MMP-2, and MMP-9." (PMID 31511625, 2019). "In another study carried out by Husain and colleagues, it was demonstrated that δ-T3 inhibited biomarkers of tumor angiogenesis (VEGF and MMP-9) in pancreatic cancer cells (L3.6pl and MiaPaCa-2) in vitro and decreased the expression of CSCs cell surface markers (CD31 and CD44)." (PMID 30717416, 2019). "And the remodeling of tumor interstitial microenvironment was shown by the expression of TGFβ1, epidermal growth factor (EGF), fibroblast activation protein alpha (FAPa), matrix metalloprotein 9 (MMP9)." (PMID 31528217, 2019).
tumor (continued). "These biomarkers include ADAM17, MMP2, MMP9, and MMP11, survivin and CK19, vimentin, CXCR4, ING5, and Stanniocalcin2; in all of these examples, these molecules are overexpressed in tumoral GC tissues." (PMID 31249523, 2019). "Except for EMTs, MMPs are also found to contribute to tumor recurrence, and 12-HETE could induce MMP9 expression." (PMID 31831037, 2019). "Moreover, knockdown of CLEC5A downregulated protein level of MMP‐2, MMP‐9, PCNA and Akt phosphorylation in tumour tissues." (PMID 30834619, 2019). "The effect of ANGPTL2 in induction of tumor cell metastasis via different protein in different type of cancer have been reported, such as integrin α5β1, p38 mitogen activated protein kinase (MAPK), and matrix metalloproteinase (MMP)-9." (PMID 31384179, 2019). "The expression and activity of MMP9 in serum as well as tissue samples correlated with histology and tumor stage, without a reference to performance status." (PMID 31191742, 2019). "To test the hypothesis that DKK1 promotes tumor invasion, we performed gelatin zymography, western blot and qPCR to assess the expression pattern of gelatinases (MMP-2, MMP-9)." (PMID 31568519, 2019). "The MMP-9 shows a similar response to that determined by proteomics analysis where an increase in tumor was observed as compared to the non-cancer tissue (UII)." (PMID 31889941, 2019). "In addition, we measured angiogenesis-related biomarkers and found that miR-632-mimic upregulated MMP9 and CD34 expression in tumour tissues." (PMID 30612555, 2019). "Luteolin inhibited tumor migration and invasion by suppressing MMP-9 in MDA-MB-231 cells at non-cytotoxic concentrations." (PMID 31611756, 2019). "Similar to the results obtained by others, we have not found a correlation between MMP-9 expression in cancerous tissue in tumor stroma and the T stage of the TNM classification." (PMID 31143300, 2019). "The limitations of our study was a relatively small sample size, due to the rarity of MM and the lack of comparative data on tumor tissue MMP9 expression levels." (PMID 31191742, 2019). "CA can act by preventing the production of ROS (reactive oxygen species), inducing DNA oxidation of cancer cells, as well as reducing tumor cell angiogenesis, blocking STATS (transcription factor and signal translation 3) and suppression of MMP2 and MMP-9 (collagen IV metalloproteases)." (PMID 31293975, 2019). "In conclusion, we observed increasing recruitment of VEGFR1+CD133+ HPCs to the lung during tumor metastasis and found high expression of CXCL-16, IL-2Rα, IL-2Rγ, MMP-1, MMP-9, PDGFR-α, SDF-1α, TGF-β, PECAM-1, and VE-cadherin in highly metastatic MDA-MB-435s cells." (PMID 30483898, 2019). "Moreover, the downregulation of LRG-1 also reduced the expression of critical factors participating in tumor metastasis, including MMP-2 and MMP-9." (PMID 30760292, 2019). "Similarly, the indicators for tumor development and progression, MMP-2 and MMP-9 were also inhibited by KLF8 silencing, which just proved the alterations of tumor malignancies at molecular level." (PMID 31827393, 2019). "For this reason, we evaluated whether IL-32θ could regulate the epithelial marker, E-cadherin, and other tumor-promoting factors, COX-2 and MMP-9, stimulated by macrophages." (PMID 31126309, 2019). "The identification of a synchronized overexpression pattern between MMP-9 and VEGF may generate many insights into tumor biology and pathogenesis." (PMID 31311559, 2019). "MMP-9 in particular, has a significant role in this process by activating vascular endothelial growth factor (VEGF), which is one of the major contributors to the formation of new vessels and tumor growth." (PMID 31839881, 2019). "Furthermore, the mRNA levels of various tumor-promoting factors including COX-2, MMP-9, E-cadherin, and GM-CSF were down-regulated in the MDA-MB-231-IL-32θ group." (PMID 31126309, 2019). "CD147 and MMP-9 expression led to EGFR expression and contributed to tumor progression." (PMID 31744072, 2019).
tumor (continued). "Moreover, NFκB activation in mesenchymal GBM cells mediates cell migration and tumor invasion through upregulation of NFκB target genes, including cell chemoattractants (IL-8, MCP-1) and matrix metalloproteinases (MMP-9)." (PMID 31467533, 2019). "The anticancer effect of SeHAN is mediated by the suppression of tumour invasion but not proliferation, as indicated by the reduction of matrix metallopeptidase-9 (MMP-9; invasion marker) and the lack of change in Ki-67 level (mitotic marker)." (PMID 31731474, 2019). "Lysophospholipids and adrenomedullin stimulate insertion of the channel into the plasma membrane, and the subsequent TRPV2-mediated Ca2+ influx increases invasiveness of tumor cells via the direct regulation of key proteases such as MMP2, MMP9, and cathepsin B." (PMID 31288452, 2019). "Also, MMP-9 and MMP-2 played an important role in the prediction of tumor recurrence and survival in HCC patients after surgical resection." (PMID 31831037, 2019). "MMPs are a family of zinc-dependent matrix-degrading proteases that have a crucial role in tumor metastasis, in which MMP2, MMP9, and MMP14 are the three major proteinases among MMP subfamily members involved in pericellular proteolysis associated with cell migration." (PMID 31093311, 2019). "HCC cells with increased serine protease inhibitor Kazal-type- (SPINK-) 6 expression associate a significant downregulation of MMP-20, as well as MMP-9, suggesting that MMP-20 may also play a role in ECM degradation and tumor cell invasion and migration." (PMID 31886121, 2019). "Compared with TBD0207B (the back side of the tumor), TBD0220L (the left side of the tumor) exhibited higher infiltration of tumor cells into normal tissues and higher expression of the invasive protein MMP9 by the HE and immunohistochemistry (IHC) staining." (PMID 31754093, 2019). "It has been reported that LCN2 can form a complex with matrix metalloproteinase-9 (MMP-9), thereby preventing MMP-9 degradation and enhancing its activity in vitro, which may also enhance tumor invasion." (PMID 31500632, 2019). "Localization of MMP-9 on the surface of keratinocytes depends on its interaction with CD44 which activates transforming growth factor-β (TGF-β), and is essential for the promotion of tumor invasion and angiogenesis." (PMID 31579438, 2019). "Since tumor cells dissolve Matrigel by secreting matrix metalloproteinases, we used the Western blotting assay and found that knocking down KIF20A can decrease the expression of MMP2 and MMP9 in C4-2 cells." (PMID 31565099, 2019). "Since matrix metalloproteinases (MMPs) promote tumor metastasis by degrading the extracellular matrix (ECM), western blotting and gelatin zymography were used to measure the relative amounts of MMP-2 or MMP-9." (PMID 31531187, 2019). "Further, tumor progression leads to origin of foci of poorly differentiated adenocarcinoma that produces its own MMP-9, making the tumor independent of mast cells." (PMID 31547070, 2019). "In our study, we have not found significant differences in MMP-9 expression in cancerous cells and tumor stroma as per the clinical stage." (PMID 31143300, 2019). "This upregulation in MMP expression might have enhanced the motility of these cells because the invasion of tumor cells is mainly dependent on the degradation of extracellular matrix by MMP-2 and MMP-9." (PMID 31572058, 2019). "Meanwhile, type I IFNs from tumor trigger differentiation of neutrophils to achieve an anti-tumoral phenotype, reducing not only CXCR4 expression in neutrophils which mediates tumor-homing, but also VEGF and MMP9 expression." (PMID 31474975, 2019). "The mentioned study also showed that the prognostic value of MMP-2/MMP-9 overexpression was independent of other tumor prognostic factors like tumor size, depth, and the number of lymph nodes involved in lymph node metastasis." (PMID 31582999, 2019).
tumor (continued). "We found the expression of THBS1 and MMP9 to be increased in LRIG2‐TG mice 48 h after TPA application, assuming that THBS1 expression could be involved in LRIG2‐mediated tumor initiation and progression." (PMID 31580518, 2019). "The absence of MMP-9 led to increased interleukin 6 levels in the bone marrow, which activated tumor cell STAT3 signaling and promoted PDAC invasion and metastasis." (PMID 31214203, 2019). "Using MMTV-PyMT; MMP9 KO mice i.v.-injected with VO-PyMT cells, we found that MMP9 KO mice have reduced lung metastasis with no change in primary tumor burden." (PMID 31727800, 2019). "In addition, we further performed immunohistochemical staining of MMP-9 and STAT3 in HCC tumor specimens." (PMID 30609841, 2019). "After release from the neutrophil granules, MMP-9 plays a pro-tumor role through mechanisms such as remodeling of ECM by degradation of extracellular proteins (such as type IV collagen), membrane cleavage, or activating pro-tumor factors including TGF-β." (PMID 31010242, 2019). "Finally, to assess protein expression changes in NeuT tumors after short-term treatment (7d) with anti–MMP-9, anti-PDL1, or the combination treatments, we performed Luminex analysis on tumor lysates." (PMID 30500835, 2018). "Furthermore, xenograft tumor models were established to verify the effects of miR‐144‐3p on tumor formation and EZH2, VEGFA, MMP2 and MMP9 expressions in vivo." (PMID 30280514, 2018). "Both TWIST1 and MMP9 play vital roles in EMT and tumor metastasis." (PMID 29348395, 2018). "We showed that MMP-9 inhibition coupled with immune checkpoint blockade (eg, anti-PDL1) may be an effective anti-tumor treatment, as the combination resulted in increased TCR diversity and Th1 response in tumors." (PMID 30500835, 2018). "Whereas at the superficial area of the tumor ALCAM correlated with the E-Cadherin/β-Catenin adhesion complex, at the invasive front ALCAM could be shed by MMP-9 in poor prognosis scenarios." (PMID 29682175, 2018). "Its members MMP-9 and MMP-2 are closely related to tumor metastasis." (PMID 30580327, 2018). "To follow how LN5 was elevated in acinar formation and tumor cell reversion, we postulated that it could be due to LN5 protein stabilization due to suppression of MMP-9 transcription." (PMID 29560860, 2018). "MMP-9 is a gelatinase that directly degrades ECM, thereby modulating the tumor microenvironment." (PMID 30271341, 2018). "Moreover, we demonstrated that CTHRC1 promoted tumour invasion by regulating MMP7 and MMP9 expression, which is mediated by the AP-1/c-Jun and NF-κB pathways, respectively." (PMID 29631554, 2018). "We conclude that NOX4-mediated mtROS signaling increases MMP9 mRNA stability and affects cancer invasiveness but not tumor growth." (PMID 30281903, 2018). "Also, matrix metalloproteinase 9 (MMP9), a metalloproteinase responsible for breakdown of the BM in tumour invasion, is strongly upregulated in the Rf-FTMs." (PMID 29551776, 2018). "Moreover, IL-32 by promoting production of MMP2, MMP9, IL-8, and VEGF facilitates invasion as well as migration of tumor cells." (PMID 30402092, 2018). "While at the superficial tumor, uncleaved ALCAM maintained a correlation with the major adhesion complex E-Cadherin/β-catenin; at the invasive tumor, where a more mesenchymal microenvironment takes place, it correlated with COX-2, SNAIL, MMP-9 and ETV5 mesenchymal markers." (PMID 29682175, 2018). "Aptamers have been used to detect a variety of cancers by targeting tumor markers, such as nucleolin, tenascin, prostate-specific membrane antigen (PSMA), MUC1, annexin A2, and matrix metalloprotease-9 (MMP-9)." (PMID 29301363, 2018). "TAMs induce EMT of tumor cells by secreting factors such as interleukelin-6 (IL-6), interleukelin-8 (IL-8), tumor necrosis factorα (TNFα), TGFβ, EGF, VEGF, matrix metalloproteinase-2 (MMP-2) and MMP-9." (PMID 30157906, 2018).
tumor (continued). "At low concentrations, capsaicin favors EMT transition by inhibiting E-cadherin expression, sustains tumor cell migration by inducing over-expression of MMP2 and MMP9 and activates Akt/mTOR signaling pathway, molecular events that together enhance the migration and invasive potential of SW480 cells." (PMID 30487390, 2018). "Matrix metalloproteinase-9 (MMP-9) can disrupt the major components, extracellular matrix (ECM), and type IV and V collagen and gelatin; and for this reason, their activity is closely related to the invasion and metastatic ability of tumor cells." (PMID 29651326, 2018). "For example, bone marrow derived cells home to the treated tumor site, and secrete MMP9 which contributes to the dissemination of tumor cells from the primary tumor and induces epithelial-to-mesenchymal transmission (EMT) in tumor cells, thereby accelerating metastasis." (PMID 29416793, 2018). "Activities of MMP-2, MMP-9, and uPA in plasma in the tumor control mice were significantly higher than those in the normal control (p < 0.05)." (PMID 29794990, 2018). "Moreover, NF-κB signal pathway seemed to be able to suppress tumor cell migration by blocking MMP-2 and MMP-9 expression." (PMID 30519264, 2018). "MMP‐9, an enzyme secreted by various tumor cells, including B16F10 cells, can degrade the extracellular matrix, facilitate detachment and invasion, and enhance tumor cells entry into blood vessels." (PMID 30479911, 2018). "Matrix metalloproteinase-9 (MMP-9) released from N2 TANs could enhance the process of extravasation through degradation of extracellular matrix, reduce apoptosis of tumor cells and increase tumor proliferation." (PMID 29930287, 2018). "Previous studies indicated that MMP-9 production was influenced by the TME, suggesting that the stroma may act as a key facilitator of tumor invasion." (PMID 30301152, 2018). "Two MMPs were identified based on their respective molecular weight corresponding to MMP9 (92 kDa) and MMP2 (72 kDa) Analysis of the relative amount of enzyme in the tumour cell conditioned medium showed a dose-dependent expression of MMPs activities with a predominant activity for MMP2." (PMID 29563634, 2018). "Several tumor-promoting genes such as CXCR4, LSH, MMP9, and hypoxia-inducible factor (HIF)-1α are thought to contribute to radioresistance, and their elevated expression is consistent with their proposed role in cancer progression, metastasis, and radiotherapy." (PMID 29706625, 2018). "Indeed, mRNA expression of human MMP-2, MMP-9 and MMP-14 (MT1-MMP) was upregulated by PTX treatment and MT1-MMP protein became abundant in E-cadherin- mesenchymal tumor cells." (PMID 29507310, 2018). "We further investigated the effect of HOXC6 expression on prognosis independent of tumor invasiveness by using MMP-9 marker as an indicator for invasive potential of tumor cells." (PMID 29348394, 2018). "In consideration of the Shh and Gli-1 results, we can speculate that the decreased MMP-2 and MMP-9 levels may be due to the inhibited activity of the Hh signaling pathway by high intracellular DOX concentrations, thus inhibiting tumor invasion and migration." (PMID 29157266, 2017). "Because studies indicate that high levels of MMP9 expression are observed in most NPC tissues, the interaction between MMP9 and IGFBP-1 in NPC tumours may contribute to NPC patients with higher levels of IGFBP-1 and an unfavourable survival." (PMID 28143425, 2017). "We also observed that MMP9 but not MMP2 was overexpressed in tumor parts (mean dCT of tumor vs. normal tissue: 1.30 vs. 3.43, p < 0.0001), and that increased MMP9 in early and advanced stages in 60 paired NSCLC tissues was correlated with MIAT." (PMID 29228680, 2017). "Whether this finding could be due to a race-related difference in the tumor’s responsiveness to bevacizumab is deserving of further study to fully evaluate if ANGPT1, ANGPT2, TEK, FGF2, MMP9 and VEGFA are promising targets for future research." (PMID 28045923, 2017).